IL15 (interleukin 15)
Diseases named in the same sentence as IL15 in open-access papers (continued):
Sharing a sentence is not in itself a finding about the gene and the disease.
melanoma (continued). "Efficacy was observed with IL-15 in multiple murine immunotherapy trials including the syngeneic TRAMP (transgene adenocarcinoma mouse prostate) -C2 prostatic cancer, Pme1-1, B16 melanoma, MC38 and CT26 colon carcinoma models suggesting that IL-15 might be more effective than IL-2 in cancer therapy." (PMID 32508818, 2020). "Therefore, transgenic expression of IL-15 seemed like an appealing strategy to enhance CAR-T cell effector function, by enhancing proliferation and persistence of CAR-T cells in the TME and has been used in preclinical models of acute myeloid leukemia (AML), melanoma, glioblastoma or neuroblastoma." (PMID 35211124, 2022). "Thus, continuous stimulation with IL-15 hyperagonist over time could lead to NK cells becoming hypo-responsive and therefore incapable of killing HLA-I low/negative melanoma cells, and also to dysfunctional TRM-like cells being unable to eliminate HLA-I positive melanoma cells." (PMID 37334356, 2023). "Although there is no data regarding levels of circulating IL-15 in relation with antiPD1/PDL1 efficacy, a previous study showed that low serum IL-15 levels correlates with better responses to antiCTLA4 treatment in melanoma." (PMID 39199571, 2024). "Furthermore, we demonstrated that IL15-induced NK1.1+CD8+ T cells, unlike unstimulated NK1.1−CD8+ T cells, are effector cells with cytotoxic function against B16 melanoma cells." (PMID 30333822, 2018).
viral infection (114 papers, 2008 to 2025). "Loss of IL-15 during viral infection impairs NK cell maturation and innate IFN-γ production, resulting in increased HSV-2 viral titers compared to WT mice." (PMID 35512020, 2022). "IL-15 is a pluripotent antiapoptotic cytokine implicated in both the innate and adaptive immune response to viral infection and cancer, and has been postulated as a highly promising immunomodulatory agent in cancer therapy." (PMID 23577098, 2013). "As α/β IFNs are induced during viral infections and are implicated in IL-15 induction in other systems, we next investigated RV induction of IFN-α/β in macrophages." (PMID 21779162, 2011). "For NK- as well as CD8 T-cell-controlled viral diseases, these may be exacerbated IL-15 deficiency, while loss of IL-15 may help viral infection that causes lymphoproliferative dysfunction." (PMID 36742132, 2023). "Interestingly, elevated IL15 levels have been associated with dysfunction of IR phagocytic cells and an ineffective response to viral infections." (PMID 34829906, 2021). "Finally, Campisciano detected an increase of the relative vaginal abundance of Prevotella timonensis in women infected with HPV, which showed a decreased concentration of the IL-15, IL-7, and IL-9 that they associated with the virus infection." (PMID 33488574, 2020). "Transgenic mice showing increased expression of IL-15 had similar improvements in wound healing but notably had decreased protection from viral infections, such as HSV-2." (PMID 40149931, 2025). "NK cells, the first donor-derived lymphocytes to recover, are promoted by the interleukin-15 (IL-15) rich cytokine milieu post-transplant, they help control residual malignant cells and viral infections." (PMID 40636378, 2025). "It is now clear that NK cells remember previous activation events with distinct forms of innate memory and memory-like responses following hapten exposure, viral infection, and combined activation with IL-12, IL-15, and IL-18." (PMID 40729303, 2024). "NK cells exhibit higher levels of YTHDF2 compared to other immune cells, and YTHDF2 expression is significantly upregulated in NK cells upon activation by tumors, viral infections, and cytokines, such as IL-15." (PMID 39686999, 2024). "IL-15 production can be induced through Type-I interferon (IFN) signaling in response to viral infections such as HIV." (PMID 37766318, 2023). "For these reasons, IL-15 has been under investigation for treatment of cancer and viral infections, including HIV." (PMID 37766318, 2023). "Bystander T-cell activation was observed to occur during viral infection and is likely driven by IL-15." (PMID 37310006, 2023). "Studies in mice and humans have revealed important metabolic pathways that sustain NK cell effector functions in the context of tumors and viral infection, as well as potential strategies for “arming” NK cells for these environments such as IL-15 priming." (PMID 36710923, 2023). "In sum, these data show that IL-15 promotes the self-renewal of Tpex cells in vivo, supporting their maintenance during chronic viral infection." (PMID 37409128, 2023). "The cytokine IL-15 is induced during many acute viral infections and is important for tissue-resident lymphocyte maintenance." (PMID 37809077, 2023). "It is well established that IL-15 is necessary to maintain and activate NK and NKT cells subpopulations; in HIV patients, the viral infection causes activation and expansion of NK cells, and the NK cells subpopulations show an abnormal frequency." (PMID 35053573, 2022). "The levels of IL-15 in peripheral blood or tissue have been shown to be increased in many viral infections, such as HIV, HAV, simian immunodeficiency virus, DENV, and respiratory syncytial virus infection." (PMID 36590594, 2022). "Our study revealed that IL-15 level was highly increased in the T1D–AdV+ group, most probably due to viral infection, as in the case of enterovirus infection and coxsackievirus B4." (PMID 36291430, 2022).
viral infection (continued). "Interestingly, IL-15 serum levels were shown to be associated with pediatric viral bronchiolitis severity, which might indicate that NK cells activated by IL-15 could play a harmful role in the course of viral infection." (PMID 33815404, 2021). "The same group showed that upregulation of IL-15 occurred after viral infection and that induction of IL-15 was dependent on the type I interferon (IFN) receptor IFNAR." (PMID 34681751, 2021). "During a viral infection, IL-15 is usually upregulated to induce proliferation of NK cells and memory T cells." (PMID 33912464, 2021). "In the context of viral infection, IL-15 is a key mediator in NK cell control of viral replication via cytotoxicity." (PMID 33815404, 2021). "IL-15 signaling induced by viral infections is vital in converting naïve immune cells, particularly T cells and NK cells, into effector cells capable of expansion and ultimately pathogen recognition and elimination." (PMID 34578331, 2021). "The cytokine IL-15, which is produced by mononuclear cells and contribute to the protection against viral infection was also a protective factor." (PMID 33722194, 2021). "IL-15 and IL-15R are important for survival and expansion of antigen specific NK cells, the mechanisms of differentiation into memory phenotype following viral infections are not clearly understood." (PMID 34516566, 2021). "IL-15 is secreted after viral infection to induce the proliferation of NK cells to kill virally infected cells." (PMID 34504500, 2021). "Virus infections result in an inflammatory environment with an increased IL-15 and TNFα and the subsequent recruiting of antigen-presenting cells to the infection site, leading to the induction of an adaptive immune response." (PMID 34211465, 2021). "IL-15 is a proinflammatory cytokine, secreted mainly by mononuclear cells following viral infection." (PMID 34830523, 2021). "Given the formidable efficacy in enhancing NK cell development, IL-15 is much more promising than other cytokines in controlling tumor progression and viral infections." (PMID 33815365, 2021). "Upon most viral infections, cDCs produce IL-12, IL-15, and IL-18 (22, –, 24), whereas pDCs rapidly produce large amounts of type I IFNs and also IL-12 (25, –, 27)." (PMID 28904191, 2017). "Noteworthy, the cytokines of crucial importance for clearing a viral infection, such as the Th1 cytokines IFNγ, and IL‐15, the pro‐inflammatory cytokines IL‐1β, IL‐6, TNFα, and TNFβ/lymphotoxin, were downregulated." (PMID 28805308, 2017). "In asthmatics IFN-γ, CXCL10/IP10, CXCL11/ITAC, IL-15 and IL-5 increased in bronchial lining fluid following viral infection (all P < 0.05)." (PMID 28373098, 2017). "During acute high-dose FV infection, IL-15 production was induced, suggesting that strong virus replication can trigger IL-15, most likely due to the activation of macrophages and cDCs that sense virus infection." (PMID 28904191, 2017). "Taken together, the results demonstrated the central role of PI3K–AKT–mTORC1 pathway in IL-15-induced NK cell activation of effector functions during virus infection." (PMID 26257729, 2015). "Prior studies suggested a role for cross-presentation of IL-15 by dendritic cells as a critical component in NK cell responses during viral infections." (PMID 26720279, 2015). "During virus infection this can be achieved via DC-presented IL-15/IL-15Rα, an interaction described as the regulatory synapse." (PMID 25412359, 2014). "Viral infections (experimentally mimicked by poly I:C) and IL-15 have been suggested as critical triggers for the damage mechanisms that occur in the small intestinal mucosa during the early stages of CD." (PMID 24586509, 2014). "IL-15 not only mediates NK cell proliferation during viral infections but also plays a critical role in NK cell development and homeostasis." (PMID 24068905, 2013).
viral infection (continued). "IL-2 and IL-15 are structurally homologous to Th1 or Th1 related cytokines produced by mononuclear phagocytes and other cell types in response to viral infection." (PMID 24358317, 2013). "Cytokines and chemokines that showed limited response in mice with any viral infection included Eotaxin, GM-CSF, IL-1α, M-CSF, IL-2, IL-3, IL-4, IL-5, IL-7, IL-9, IL-12p40, IL-13, IL-15, IL-17, MIP2, LIX, MIP1β, RANTES, IL-12p70, and VEGF (data not shown)." (PMID 23441208, 2013). "Many factors, such as UV radiation, cytokines (e.g., IL-1β, TNF-α, IFN-γ, and IL-15), viral infections (hepatitis B or C, HIV infection) can induce expression of Fas in epidermis." (PMID 22778762, 2012). "Elevated IFN-γ expression is an important immunological marker in the pathogenesis of HAM/TSP, and CD8+ T cell dysregulation was mediated by various factors, including virus infection, enhanced IL-2/IL-15, and expression of cellular molecules." (PMID 22335964, 2012). "In previous studies, IL-15 was found to enhance severity of endotoxin shock liver injury, colitis and virus infection." (PMID 23028657, 2012). "Critical and coordinated functions of IFN-α/β, IL-12, and IL-15 in regulating NK cell responses during viral infections have been reported." (PMID 22340040, 2012). "IL-15 is critical for NK cell-dependent clearance of several viral infections, in particular infections by human herpesviruses." (PMID 22253598, 2012). "IL-15 has been shown to be particularly important in providing a protective immune response to viral infection." (PMID 21991302, 2011). "Continued work targeting the quantification of IL-15 levels during viral infection at different time points is necessary for further clarification of this data." (PMID 21991302, 2011). "Based on these in vitro data, we favor the idea that the detection of activated/proliferating HCMV and EBV specific CD8 T cell is mediated principally by the presence of IL-15 during acute phase of viral infections." (PMID 20808900, 2010). "IL-15, which is produced during acute viral infections, is the likely contributing mechanism driving the selective activation of herpesvirus specific CD8 T cells." (PMID 20808900, 2010). "IL‐15 is a promising cytokine for treating cancer and viral diseases." (PMID 40799128, 2025). "Furthermore, IL-6 together with IL-15 regulates the cytotoxic function of the CD8+ T cells as the main adaptive immune cells in viral infections." (PMID 39062668, 2024). "NKG2A/C+CD8+ T cells have been reported to be macaque innate-memory cells, whose expansion is induced by IL-15 and may contribute to controlling viral infection." (PMID 39524802, 2024). "The effect of IL-15 on the outcome of viral infections greatly varies from virus to virus." (PMID 36742132, 2023). "While the degree of IL-15 overproduction is mild compared with MAS, elevated IL-15 levels may be a risk factor for the development of MAS associated with SLE and viral infections." (PMID 37751296, 2023). "In particular, IFN‐I, IL‐12 and IL‐15 have established roles in viral infection and NK activation." (PMID 35156714, 2022). "However, elevated levels of various cytokines including IL-12, IL-15, IL-18 or type I interferon are commonly seen in the context of viral infection." (PMID 36374780, 2022). "The obtained results may confirm the data on the role of IL-4 and IL-15 in mediating the development of specific CD8+ T cell memory during viral infections, which was confirmed by in vivo studies." (PMID 35632739, 2022). "IL-10 and IL-15 are both vital immune mediators against viral infections, especially IL-10." (PMID 33912464, 2021). "In one study, it was also seen that the addition of IFN-α, an important cytokine in viral infection and an inducer of IL-15, to IL-15-driven CD8+ memory T cells could further increase SRC." (PMID 33927722, 2021).
viral infection (continued). "Furthermore, we observed elevated levels of CXCL8 and CCL2 that promote the recruitment of non-adaptive immune cells to the liver such as monocytes, the main source of IL-15 and IL-18 during viral infections." (PMID 33617602, 2021). "Furthermore, memory-like properties of NK cells, with elevated cytotoxicity, can be obtained upon repeated exposure to either viral infections in vivo or combined pre-activation of IL-12, IL-15, and IL-18 cytokines ex vivo." (PMID 33920906, 2021). "In RMs, natural plasma IL-15 levels during acute SIV were significantly positively correlated with viral infection of CD4+ T cells, and this was attributed specifically to an increase in CD4 on the surface of memory CD4+ T cells between day 7 and 10 in acute SIV." (PMID 34578331, 2021). "The phenotypes presented in pre-activated hypoxic NK cells are quite similar to those recently described for adaptive/memory NK cells, showing enhanced recall responses following either a viral infection or combined IL-12, IL-15, and IL-18 cytokine stimulations." (PMID 33920906, 2021). "Because IL-15 is one of the first cytokines to be produced in response to acute HIV infection and IL-15 can be induced by viral infections, it is conceivable that viral replication can promote IL-15 signaling, thereby enabling chronic immune activation and disease progression." (PMID 34578331, 2021). "In the context of viral infection, the cell death program of IECs is regulated by their upregulation in the expression of IL-15, which is a cytokine capable of stimulating the activation of CD3+NK1.1+ IELs and inducing perforin-mediated killing of virus-infected epithelial cells." (PMID 32328062, 2020). "Cytokines such as IL-1-6, IL-12, and IL-15 show promise as vaccine adjuvants, because they may increase the rates of survival against different virus infections." (PMID 32802975, 2020). "IL-15 has an anti-apoptotic effect on cytotoxic cells, therefore keeping them in play and being capable of killing a high number of infected cells in the case of viral infections." (PMID 32674433, 2020). "Moreover, IL-15 priming can reduce this glycolytic requirement for NK cell cytotoxicity, highlighting the therapeutic potential of IL-15 in viral infections." (PMID 32983138, 2020). "For instance, NKp30 and NKp44 are highly induced on Vδ1+T cells after continued activation by γδTCR stimulation in the presence of IL-2 or IL-15, and the inducible NCRs endows Vδ1+T cells with enhanced cytotoxicity against leukemia cells and increased ability to control of virus infection." (PMID 30930903, 2019). "Moreover, alcohol consumption decreased IL-15-producing DC after 36 hours infection, inhibited NK cell, specifically Ly49H+ NK cell maturation and proliferation 3-6 days after viral infection." (PMID 32123809, 2018). "However, the analysis of IL-15 showed a >4-fold increase of mRNA levels after high-dose viral infection compared to those in naive mice, whereas infection with a medium dose of FV did not result in upregulation of IL-15 mRNA expression." (PMID 28904191, 2017). "Our results suggest that NK cell activity may be therapeutically enhanced by administering IL-15 and IL-18 in virus infections that inadequately activate NK cells." (PMID 28904191, 2017). "Moreover, deficient expression of iOPN in NK cells causes impaired expansion and increased apoptosis of these cells following stimulation with interleukin 15 (IL-15), resulting in defective immune response to viral infection and tumor." (PMID 29267211, 2017). "So how does IL-15 fulfill such heightened metabolic demands in NK cells during virus infection?" (PMID 26257729, 2015). "mTORC1 activity is greatly increased in mice treated with poly IC (a mimic of virus infection and inducer of IL-15 expression) or infected with MCMV, as exemplified by the drastic increase in the mTORC1-mediated phosphorylation of S6 ribosomal protein, a downstream target." (PMID 26257729, 2015).